SELENOV (selenoprotein V)
Description:
May be involved in a redox-related process.
Synonyms: SelV
Tractability: PROTAC: UniProt records ubiquitination sites on it.
Gene: Protein-coding gene on chromosome 19 (39,515,139 to 39,520,675, forward strand). Ensembl gene ENSG00000186838.
Gene Ontology:
Molecular function: protein binding
Cellular component: cytosol
Genetic constraint (gnomAD): Loss-of-function variants: 25 observed, 21.14 expected, observed/expected ratio (o/e) 1.18, 90% interval 0.86 to 1.64. The upper end of that interval is the gene's LOEUF score, 1.64, which puts it in group 6 of 6, group 1 being the genes least tolerant of losing a copy. Missense variants: 472 observed, 466.89 expected, observed/expected ratio (o/e) 1.01, 90% interval 0.94 to 1.09. Synonymous variants: 227 observed, 221.02 expected, observed/expected ratio (o/e) 1.03, 90% interval 0.92 to 1.15.
Homologues: Orthologues: chimpanzee SELENOV (96% identical), pig SELENOV (53% identical), dog SELENOV (49% identical), mouse Selenov (42% identical), rat Selenov (40% identical). Paralogues in human: SELENOW (10% identical), MIEN1 (8% identical).
Diseases named in the same sentence as SELENOV in open-access papers:
SELENOV is named in the same sentence as 8 diseases in open-access papers, as found by Europe PMC text mining. Sharing a sentence is not in itself a finding about the gene and the disease. The quoted sentences say what the papers report.
Azoospermia (1 paper, 2021). Absence of any measurable level of sperm,whereby spermatozoa cannot be observed even after centrifugation of the semen pellet. "Nevertheless, some causal links between specific selenoprotein deficiencies and phenotypes (e.g., abnormal thyroid function and deiodinase enzymes; low plasma Se and SELENOP, GPX3; azoospermia and SELENOV, GPX4, TXRND3; myopathy and SELENON) can be made." (PMID 34884733, 2021).
medulloblastoma (1 paper, 2020). A malignant, invasive embryonal neoplasm arising from the cerebellum. "Interestingly, the fraction of M2 macrophages in Group 4 medulloblastoma were positively correlated with the risk score and were significantly correlated with the expression level of four signature genes (CCNY, SYNE3, CYB5D2, and SELENOV) and four hub genes (GLI2, PAX6, RUNX2, and ZIC1)." (PMID 32508873, 2020).
cancer (2 papers, 2021 to 2025). A tumor composed of atypical neoplastic, often pleomorphic cells that invade other tissues. "On the other hand, SELENOV (SelV) is identified as the selenoprotein that only negatively correlated with ZIP8 in 10 out of 40 cancer types." (PMID 34768831, 2021).
SELENOV also shares sentences with these, for which no sentence is quoted: Cirrhosis (1 paper); gastric cancer (1); metabolic disease (1); myopathy (1); Obesity (1).